YAP1 (Yes1 associated transcriptional regulator)
Diseases named in the same sentence as YAP1 in open-access papers (continued):
Sharing a sentence is not in itself a finding about the gene and the disease.
breast cancer (continued). "Besides the changes of YAP1 expression in breast cancer tissues, it also displayed robust nuclear localization in which it is activated." (PMID 32046779, 2020). "As YAP1 is a target of the Hippo pathway, RASSF1A might suppress the growth of ERα+ breast cancer cells through activation of the Hippo kinases, leading to inhibition of YAP1." (PMID 32967092, 2020). "Using an unbiased global transcriptome and proteomic analysis of HER2-positive breast-cancer cells, we propose a new model in which acquired resistance to trastuzumab may be mediated by the increased activity of the YAP1/TEAD1-2 complex." (PMID 32365528, 2020). "The multivariate survival analysis using Cox’s regression model, which included hormonal status, ER status and YAP1 expression category (low or high), identified YAP1 overexpression as an independent indicator of bad prognosis in the cohort of HER2+ metastatic breast cancer patients (p < 0.01)." (PMID 32365528, 2020). "Finally, it was revealed that MicroRNA-200a promotes anoikis resistance and metastasis by targeting YAP1 in human breast cancer." (PMID 30619734, 2018). "All induced mice develop mammary tumours with 9qA1 (Yap1) and/or 6qA2 (Met) amplification(s)." (PMID 28194015, 2017). "Here we asked whether the regulatory effect of Yap1 on TICs could be extended to human breast cancer and predict prognosis in basal breast tumors." (PMID 26695440, 2016). "Therefore, we further utilized the ER status to differentiate these 2 breast cancer subtypes, and we examined the correlation of Yap1 expression in each of these cancer types." (PMID 26695440, 2016). "As a high deletion rate of YAP1 (45.5%, 141/310 samples) was observed in BRCA, we assume that YAP1 may also trigger apoptosis in breast cancer cells." (PMID 26099552, 2015). "We found that methylation of RASSF1-1α (representing gene silencing) significantly correlates with low pS127-YAP1 in glioma, bladder, and breast cancer cohorts, suggesting that YAP1 may be nuclear and active in RASSF1-methylated tumors." (PMID 26549256, 2015). "Furthermore, YAP1 was recently reported to function as an oncogene by promoting proliferation and survival of breast cancer cells by binding and stabilising the KLF5 (Kruppel-like factor 5) transcription factor through its PPxY motif." (PMID 24559095, 2014). "The chromosomal location of the YAP1 gene at 11q22 is also in favour of it functioning as a tumour suppressor given the frequent loss of heterozygosity (LOH) and deletions of this region in breast cancers." (PMID 24559095, 2014). "This subgroup specificity led us to hypothesize that YAP1 may be important for response to endocrine therapies, such as tamoxifen, extensively used for luminal A breast cancers." (PMID 24559095, 2014). "In addition, amplification of YAP1 in human breast cancer is infrequent and YAP1 protein expression is often decreased in primary breast cancer." (PMID 24559095, 2014). "Moreover, recent data indicated that YAP1 activity correlates with high histological grade and metastasis in breast cancer." (PMID 24810989, 2014). "The microenvironment might also constitute a critical parameter for understanding and modelling YAP1 in breast cancer, and stable downregulation of YAP1 in MCF-7 has been reported to result in increased invasion in a matrigel transwell assay." (PMID 24559095, 2014). "The role of YAP1 in breast cancer is at present a matter of debate." (PMID 24559095, 2014). "In addition, downregulation of YAP1 in the human breast cancer cell line MCF-7 resulted in decreased cell proliferation and complete loss of tumour formation in mice." (PMID 24559095, 2014).
breast cancer (continued). "The YAP1 gene is located at 11q22, a region often deleted upon amplification of the 11q13 region harbouring the known oncogene cyclin D1 gene (CCND1), which is amplified in 8-15% of all breast cancers and associated with a worse prognosis." (PMID 24559095, 2014). "There are however also reports where YAP1 show oncogenic features in ER+ breast cancer models." (PMID 24559095, 2014). "It was demonstrated that YAP1 protein expression was decreased or lost in breast cancers." (PMID 24223879, 2013). "Additionally, a randomized controlled study indicated that low YAP1 mRNA expression is an independent prognostic factor for recurrence in the less aggressive luminal A breast cancer subgroup and may contribute to progression." (PMID 40731926, 2025). "However, in breast cancer, controversies regarding the role of YAP1 in tumor biology exist." (PMID 37894401, 2023). "Therefore, the present study might be the first large-cohort study specifically comprised of HR+HER2− breast cancer with precise YAP1 IHC interpretation and validation of its clinical impact using public datasets." (PMID 37894401, 2023). "For example, YAP1 could induce basal-like breast cancer stemness." (PMID 35459269, 2022). "Therefore, our data support that YAP1 was increased in breast cancer, which might mainly originate from its increased DNA copy number and almost unchanged IL‐18." (PMID 34196131, 2022). "Thus, we conclude that RAC1 may be the key effector of YAP1-induced invadopodia formation in breast cancer cells." (PMID 35773411, 2022). "Thus, based on our analysis, we hypothesized that IL‐18 either acts as a regulatory factor in the expression of YAP1 or interacts with it to determine the occurrence and progression in breast carcinoma." (PMID 34196131, 2022). "However, the role of YAP1 in breast cancer remains controversial." (PMID 33718163, 2021). "Notably, MIR22HG stabilized the expression of large tumor suppressor 2 (LATS2), which promoted the LATS2-dependent phosphorylation of YAP1 and suppressed the expression of its downstream target oncogenes, thereby inhibiting the proliferation and migration of breast cancer cells." (PMID 34446703, 2021). "However, in breast cancer, the role of YAP1 has been still considered controversial." (PMID 33970925, 2021). "Therefore, the results suggest that the expressions of YAP1 and JAG1 are upregulated in breast cancer cells and they may be associated with advanced tumor grade and poor prognosis for breast cancers." (PMID 32046779, 2020). "Taken together these observations are consistent with the notion that suppression of YAP1 expression by RASSF1A plays a pivotal role in RASSF1A-induced cell cycle arrest and senescence, and explain mechanistically how the loss of RASSF1A contributes to ERα+ breast cancer initiation and progression." (PMID 32967092, 2020). "Finally, YAP1/TAZ nuclear accumulation in malignant cells in HER2 breast tumor was significantly associated with worse progression-free and overall survival in metastatic HER2-positive breast-cancer patients." (PMID 32365528, 2020). "Additionally, ERK1 inhibited breast cancer cell proliferation via regulation of YAP1." (PMID 31848326, 2019). "GJA1 encodes for connexin-43, a gap junction protein whose expression in breast cancer cells has been implicated in pulmonary metastasis, consistent with observed lung metastasis in both patients from which the ESR1-e6>YAP1 and ESR1-e6>PCDH11X fusions were identified." (PMID 30089255, 2018). "However, another study found that Yap1 acted as a tumor suppressor in breast cancer." (PMID 26695440, 2016). "Nevertheless, a study showed that a decrease in Yap1 expression was an independent prognostic factor for recurrence in a subgroup with a less aggressive luminal A breast cancer, which may possibly be explained by the decreased tamoxifen sensitivity that is induced by Yap1 downregulation." (PMID 26695440, 2016).
breast cancer (continued). "Importantly, our work clearly indicated that, as previously pointed out by the work of Strano, in human breast cancer cells YAP1 could be a tumour suppressor." (PMID 27322327, 2016). "In breast cancer, aggressive B-cell lymphoma and glioblastoma, USP9X alleviates tumor cell survival and confers chemoresistance through YAP1, XIAP or Mcl-1 stabilization." (PMID 40246814, 2025). "In breast cancer, it binds TEAD1, and this interaction antagonizes TEAD1–YAP1-induced cell proliferation in Hippo–YAP1 signaling." (PMID 39857952, 2025). "In breast cancer, FOXM1 has been observed at elevated levels and is known to promote breast cancer cell stemness and migration in a YAP1-dependent manner." (PMID 38978058, 2024). "ChIP-seq analysis reveals significant overlap between PML-, ER-, and Myc-bound promoters, suggesting their coordinated regulation of target gene expression, including genes involved in breast cancer stem cells (BCSCs), such as JAG1, KLF4, YAP1, SNAI1, and MYC." (PMID 37720048, 2023). "Another previous study of our group showed a correlation between YAP1 expression and tumor stiffness in HR+HER2− breast cancer tissue." (PMID 37894401, 2023). "In ER+ breast cancer cell lines, LATS1/2, upstream inhibitors of YAP1, are required to maintain ER+ cancer cell growth while little effect was observed in ER− cancer cells." (PMID 37894401, 2023). "Existing studies have dedicated less effort on investigating mechanisms associated with OTUB2, YAP1 and TAZ in ESCC, and studies have shown that in breast cancer,OTUB2 can stabilize and activate YAP1/TAZ." (PMID 35850645, 2022). "In this study, we report that YAP1, which interacts with the transcription factor TEAD4, induces invadopodia formation and promotes tumor metastasis in breast cancer cells." (PMID 35773411, 2022). "Similar to findings in breast cancer, the inhibitory effects of silencing SAPCD2 on colony formation and anchorage-independent growth capabilities were reversed by constitutively active YAP1-S127A." (PMID 35517423, 2022). "In summary, our study demonstrated that YAP1 can upregulate TIAM1 expression by binding to its enhancer, which subsequently activates RAC1 and induces invadopodia formation in breast cancer." (PMID 35773411, 2022). "Such interaction between YAP1/TAZ/TEAD-bound enhancers with promoters via chromatin looping has been reported in the MYC and TOP2A genes in an epithelial human breast cancer cell line." (PMID 35619099, 2022). "Another YAP1 target gene, COL12A1 (collagen type 12 alpha one chain), has been shown to play a role in tumor invasion and migration in gastric, colorectal and breast cancer." (PMID 35407556, 2022). "Mechanotransduction-mediated YAP1 activation establishes a feed-forward self-reinforcing loop that contributes to maintenance of the CAF phenotype and promotes breast cancer invasion." (PMID 36479120, 2022). "YAP1 and TEAD4 can also recruit mediator complex subunit 1 (MED1), an important enhancer activating machinery, to facilitate breast cancer cell growth." (PMID 35883668, 2022). "Whereas in primary breast cancer, the genetic alteration of IFNG is significantly low and IL‐18 and YAP1 showed almost same level of gene alteration." (PMID 34196131, 2022). "Another study showed that the activity of YAP1/TAZ and its target genes is promoted by the activation of Src in breast cancer and melanoma cells." (PMID 34693980, 2021). "The regulatory network TRIM24 was involved in showed that TRIM24, YAP1, Ifn, Ifnar, SOCS1, and S100A8 together activated atherogenesis and cell viability of breast cancer cell lines through 18 genes, including AKT1, ID2, etc.." (PMID 34575874, 2021).
breast cancer (continued). "On the contrary, the expression of constitutive active Src under the form of the Src Y527F mutant, led to elevated levels of YAP1/TAZ and of its target genes in several human and mouse breast cancer and melanoma cell lines." (PMID 34693980, 2021). "Particularly, in the reconstructed SYK signaling network, the proximal network of YAP1 and STK4, two Hippo pathway proteins, is almost entirely exclusive to breast cancer cells." (PMID 33670716, 2021). "Here, we show that RASSF1A decreases the levels of YAP1, and as a consequence, the suppression of FOXM1 and ERα expression and senescence in ERα-driven breast cancer cells." (PMID 34831091, 2021). "Consistent with other studies, YAP1-dependent transcription activation was high in MDA-MB-231 and HS578T breast cancer cells compared with the MCF10A normal cells." (PMID 34462427, 2021). "In breast cancer, FOXM1 was found to promote the activity of YAP1 and maintain the cancer cell stemness." (PMID 33959615, 2021). "We showed that treatment of MDA-MB-231 breast cancer cells with GLI1 siRNA induced inhibition of mammosphere formation and down-regulation of YAP1, a Hippo pathway effector." (PMID 34445421, 2021). "We analyzed mRNA expression levels of the effectors of the Hippo pathway (YAP1, TAZ, TEADs) in a series of 1097 HER2-positive breast-cancer patients from available data on TCGA and correlated with OS." (PMID 32365528, 2020). "Overexpressed linc-OIP5, YAP1, and JAG1 were found in breast cancer cell lines MCF7 and MDA-MB-231 and the expression levels of YAP1 and JAG1 were proportional to the breast cancer tissue grades." (PMID 32046779, 2020). "YAP1 dephosphorylation and TEAD2 overexpression were detected as significant alterations in the Hippo pathway in trastuzumab-resistant breast cancer." (PMID 32365528, 2020). "Hence, linc-OIP5 in MDA-MB-231 breast cancer cells may act on the upstream of the YAP1/Notch/NRP1 signaling circuit to affect proliferation, migration, and tube formation of co-cultured HUVECs in a non-cellular direct contact way through JAG1 in conditioned medium." (PMID 32046779, 2020). "In order to investigate the role of linc-OIP5, YAP1, and JAG1 in breast tumorigenesis, their expression levels in normal breast cells (MCF-10) and breast cancer cells (MDA-MB-231, MCF-7) were verified by RT-PCR." (PMID 32046779, 2020). "The immunoblot analysis further confirmed the protein expression of YAP1 and JAG1 in both breast cancer cells, which gave the same results as RT-PCR." (PMID 32046779, 2020). "Using transcriptome data of 50 breast cancer cell lines, the GSEA revealed strong enrichment of YAP1 signaling-related genes in ERK1 low expression breast cancer cell lines compared with those with high ERK1 expression." (PMID 31848326, 2019). "Consistent with ERK inhibition and ERK1/2 silencing, ERK2 knockdown decreased YAP1 expression in MDA-MB-435S, which was further validated in two breast cancer cell lines." (PMID 31848326, 2019). "TEAD2, a transcriptional enhancer factor, contributes to EMT in breast cancer and pancreatic adenocarcinoma (PDAC) by directing its co-factor YAP1 to the nucleus." (PMID 31143705, 2019). "In a mouse model, YAP1/TAZ cooperate with Her2, Polyoma‐middle T and Wnt1 to induce breast cancer development." (PMID 28782275, 2018). "We showed that miR-200a promotes DNA damage resistance by inhibiting DNA damage-induced apoptosis via YAP1 and TP53INP1 in breast cancer." (PMID 29329575, 2018). "We also analyzed the correlation between TAZ or YAP1 mRNA expression and LKB1 mRNA levels as well as the relevance between TAZ or YAP1 mRNA expression and PHGDH mRNA levels in the breast cancer dataset from The Cancer Genome Atlas." (PMID 28931725, 2017).
breast cancer (continued). "However, in ER-negative cancers (ERneg), the Yap1high status consistently had a lower survival rate in human patients compared with the Yap1low status (80/199 vs. 159/255, p< 0.05), suggesting that Yap1 may be a potential driver gene for treating this breast cancer subtype." (PMID 26695440, 2016). "YAP1 was reported to be the cancer driving gene in the human hepatocellular carcinoma (HCC) and breast cancer 11q22 amplicons." (PMID 24621512, 2014). "The up-regulation of YAP1 degradation upon elimination of USP9X enhances cellular sensitivity to chemotherapy, indicating the oncogenic role of USP9X and identifying it as a potential therapeutic target for breast cancer treatment." (PMID 40034124, 2025). "YAP1 and TEAD4 can also serve as ERα cofactors to further boost the growth of ERα(+) breast cancer." (PMID 40066231, 2025). "Importantly, the oncogenic roles of CDK4/6 and YAP1 have been identified not only in HCC, but also in many other cancers, including breast cancer, esophageal cancer, pancreatic ductal adenocarcinoma." (PMID 40307228, 2025). "While our initial focus was on the differences between luminal breast cancer and MSL TNBC, this does not mean that the role of METTL14 in determining YAP1 expression is opposite in these two breast cancer subtypes." (PMID 39563370, 2024). "For example, a resent study reported that silencing FN1 inhibits YAP1/Hippo pathway activation by enhancing YAP1 phosphorylation, reduces aspartate uptake and utilization via SLC1A3, and suppresses breast cancer cell proliferation, invasion, migration and promotes apoptosis." (PMID 39218967, 2024). "Furthermore, we investigated the relationship between the sum of YAP1 and WWTR1 expression and survival in breast cancer patients with different intrinsic subtypes." (PMID 38164185, 2024). "In breast cancer, it was found that decreased expression of miR-205 in breast fibroblasts can activate NFs to CAFs by targeting YAP1, especially without the intervention of VEGF, and CAF activation mediated by miR-205 and YAP1 can also promote angiogenesis." (PMID 37978384, 2023). "A previous study using a 3D culture of breast cancer cells suggested that YAP1 and matrix stiffness is irrelevant under absence of stress fibers." (PMID 36291755, 2022). "However, in breast cancer, genome-wide analysis of YAP1/TAZ-binding sites showed that nearly 91% of YAP1/TAZ-bound cis-regulatory regions coincided with enhancer elements located at a distance from transcription start sites." (PMID 35773411, 2022). "Till now, much information has not been known about the role of YAP1 in tumor aggressiveness and immune evasion in breast cancer with respect to IL‐18." (PMID 34196131, 2022). "In breast cancer, several studies have revealed that GPER could suppress YAP1 phosphorylation by turning off the Hippo pathway." (PMID 33237585, 2021). "Following treatment with PFD, we found that PFD significantly reduced the migration of an invasive type of breast cancer cells and CAFs, and significantly decreased the expression of EMT marker vimentin, stemness marker CD44, and YAP1 in CAF-tumor spheroids at the protein level." (PMID 34680267, 2021). "Hippo signaling pathway has become increasingly important in human cancer, the key regulator YAP1 has been certified to be up-regulated in breast cancer, CRC and liver cancer, and YAP1 could promote cell growth and inhibit apoptosis." (PMID 34132347, 2021). "YAP1 is deubiquitinated and stabilized by USP9X, accelerating cell proliferation in breast cancers." (PMID 34575114, 2021). "Taken together, these observations are consistent with the notion that suppression of the Hippo effector YAP1 by RASSF1A plays an important role in RASSF1A-induced cell cycle arrest and senescence, as well as in RASSF1A-mediated suppression of ERα-driven breast cancer." (PMID 34831091, 2021).